WFS1 (wolframin ER transmembrane glycoprotein)
Diseases named in the same sentence as WFS1 in open-access papers (continued):
Sharing a sentence is not in itself a finding about the gene and the disease.
deafness (66 papers, 2006 to 2026). An inherited or acquired condition characterized by the complete loss of the ability to hear from one or both ears. "Frequently reported findings of heterozygous variants in the WFS1 gene cause deafness and increased risk for diabetes type 2." (PMID 39767643, 2024). "Among these genes, DFNA6 (DFN = deafness, A = dominant), DFNA14, and DFNA38 are associated with low-frequency non-syndromic hearing loss (LF-NSHL), which is caused by variants of the Wolfram syndrome 1 (WFS1) gene." (PMID 39200993, 2024). "It is well reported that heterozygous mutations in the WFS1 gene cause deafness or increase the risk for type 2 diabetes." (PMID 37759745, 2023). "Remarkably, p.Ala684Val in WFS1 is associated with early-onset severe-to-profound deafness, revealing a strong candidate variant for CI." (PMID 37041640, 2023). "Specifically, WFS1 variants were present in 14.5% (N = 9) of studies, including 14 patients with severe-to-profound or profound deafness (i.e., possible CI candidates)." (PMID 37041640, 2023). "Differential diagnosis should be made with mitochondrial diseases, deafness caused by WFS1 mutations, autosomal dominant OA, Bardet–Biedl syndrome, Alström syndrome, and Friedreich ataxia." (PMID 35328914, 2022). "The WS-induced deafness is recognized as HL at middle and high frequencies, and variants in WFS1 are generally distributed throughout its coding region." (PMID 36225977, 2022). "Once a variant occurs in WFS1, ER stress is strongly induced, and endolymphatic ion composition and homeostasis are disrupted, which leads to deafness." (PMID 36564540, 2022). "All the analysis provided an indication for further study of the deafness mechanism caused by WFS1 mutation." (PMID 36564540, 2022). "In this study, we found that the WFS1 gene c.2421C>G (p.Ser807Arg) heterozygous mutation, located in exon 8, is the gene that causes deafness in this Chinese family." (PMID 36564540, 2022). "For the purpose of exploring the potential mechanism of deafness caused by WFS1 gene mutation, we have screened key genes and signaling pathways by integrated bioinformatics analysis." (PMID 36564540, 2022). "We recommended that WFS1 gene testing should be incorporated into routine examination for the genetic diagnosis of deafness, especially low-frequency hearing loss." (PMID 36564540, 2022). "Using Sanger sequencing, the WFS1 mutation (p.E830Q) was detected in 5 of the 8 family members of the 2 maternal aunts which co-segregated with deafness." (PMID 34630320, 2021). "WFS1 is also responsible for DOA associated with neurosensorial deafness and for isolated recessive isolated ION." (PMID 33841295, 2021). "Eight families with OA and deafness carrying a single, recurrent heterozygous missense mutation in WFS1 gene leading to reduced levels of mutant wolframin have been described." (PMID 25255707, 2014). "The present report describes the phenotype of a third family with autosomal dominant optic neuropathy and deafness that is associated with a novel missense mutation in WFS1." (PMID 20069065, 2010). "The present phenotype is similar to the phenotype caused by the only other reported WFS1 missense mutation (p.Gln864Lys) that causes autosomal dominant optic neuropathy and deafness." (PMID 20069065, 2010). "In this article we report a novel missense mutation (p.Lys836Asn) in exon 8 of WFS1 that is associated with autosomal dominant optic neuropathy and deafness." (PMID 20069065, 2010). "Variants in WFS1 have also been associated with several other forms of deafness." (PMID 37386014, 2023).
deafness (continued). "Of them, three were novel missense mutations (p.G38D in COCH, p.E316K in ACTG1, and p.P164R in POU4F3), one was a novel in-frame indel mutation (c.2036-2038delAGG in WFS1), and two were known deafness-causing mutations that have been previously reported (p.R653C in WFS1 and p.D572N in TMC1)." (PMID 25388789, 2014). "The WFS1 gene, however, which is responsible for Wolfram-like syndrome and deafness, cannot explain the patients’ symptoms." (PMID 39524436, 2024). "On the other hand, WFS1 gene transfer would be suitable not only for WFS1 itself, but also for other more common neurodegenerative, deafness, or diabetic syndromes." (PMID 37759745, 2023). "Although the role of WFS1 in the occurrence of diabetes and OA is well documented, little is known about its implication in deafness." (PMID 37386014, 2023). "Wolfram syndrome 1 (WFS1, OMIM 222300), an uncommon genetic disorder caused by mutations in WFS1 gene (wolframin protein), is accompanied by optic nerve atrophy, deafness, diabetes insipidus and diabetes mellitus." (PMID 32231131, 2020). "The differential diagnoses include mitochondrial disorders, mutant WFS1 gene-induced deafness, autosomal dominant optic nerve atrophy, Friedreich ataxia, Bardet–Biedl syndrome, and Alstrӧm syndrome." (PMID 26742931, 2016). "After applying a filtering strategy using GEM.app followed by validation and segregation analysis of the variants in the family, we identified new deafness causative mutations in the MYH14 and WFS1 genes in part B and C of the composite family, respectively." (PMID 25289672, 2014). "Heterozygous mutations in the WFS1 gene have been associated with insulin-independent diabetes mellitus (OMIM:125853), Wolfram-like syndrome (OMIM:614296), deafness (OMIM:600965), and cataracts (OMIM:116400), following an autosomal dominant inheritance pattern." (PMID 40149731, 2025). "Likewise, p.Ala684Val in WFS1 was responsible for early-onset severe-to-profound deafness in all affected patients, suggesting a close genotype-phenotype correlation." (PMID 37041640, 2023). "We identified two previously reported heterozygous WFS1 mutation (NM_006005.3: c.2051C>T, p.A684V and c.2590G>A, p.E864K) in exon 8 and no candidate pathogenic variants in the other 127 deafness genes in the sporadic cases." (PMID 32567228, 2020). "Among these loci, which are designated DFNA (DFN = deafness; A = dominant), DFNA6, DFNA14, and DFNA38 are associated with low-frequency nonsyndromic sensorineural hearing loss (LF-NSHL) and caused by a heterozygous mutation in the Wolfram syndrome 1 (WFS1) gene." (PMID 29258540, 2017). "TMPRSS3, MYO15A, GJB2, SLC26A4 were found to be responsible for deafness in autosomal recessive or sporadic families, while TECTA, WFS1, MYH9, EYA1, COL4A5 and COL11A1 were identified as the responsible genes for deafness in autosomal dominant families." (PMID 23967202, 2013). "TECTA, WFS-1, MYH9, EYA1, COL4A5, COL11A1 were identified as the responsible genes for deafness in autosomal dominant families." (PMID 23967202, 2013). "On the basis of this study we advise to perform extensive genetic testing of at least WFS1 and OPA1 in cases of autosomal dominant optic neuropathy and deafness." (PMID 20069065, 2010). "Hotspot mutations in the deafness-associated genes are not uncommon, and have been reported for KCNQ4, ACTG1, WFS1, and TECTA." (PMID 32486382, 2020).
hearing loss (44 papers, 2007 to 2026). "When comparing previously reported cases of autosomal dominant WFS1 gene-associated hearing loss, most of the patients in this study showed severe-to-profound bilateral sensorineural hearing loss (genotype–phenotype correlation)." (PMID 39858604, 2025). "In our previous study, we performed massively parallel DNA sequencing analysis for 10,047 independent Japanese patients with hearing loss and identified 94 cases with autosomal dominant WFS1 gene-associated hearing loss." (PMID 39858604, 2025). "Here, we reported the findings for 14 hearing loss patients from 13 independent Japanese families with the heterozygous p.A684V variant in the WFS1 gene." (PMID 39858604, 2025). "Ten patients with pathogenic variants of WFS1 exhibited non-syndromic hearing loss with an autosomal dominant inheritance pattern, consistent with DFNA6/14/38." (PMID 39200993, 2024). "In comparison with our previous study on 511 survivors where rs62283056 in WFS1 was significantly (p = 1.4 × 10−8) associated with hearing loss, in this study of 606 survivors, the association was of borderline significance." (PMID 35322580, 2022). "The WFS1-associated nonsyndromic hearing loss has two types: autosomal dominant hearing loss, characterized by low-frequency decline, and autosomal recessive hearing loss, characterized by congenital profound sensorineural deafness." (PMID 36564540, 2022). "In contrast, some dominant de novo WFS1 variants are known to cause severe neonatal-onset diabetes, congenital sensorineural hearing loss, congenital cataracts, and developmental delays, which are known as WFS1-related disorders." (PMID 36613674, 2022). "Generally, ADNSHL patients with WFS1 mutations mostly have progressive, bilateral sensorineural hearing loss." (PMID 36564540, 2022). "rs62283056 in WFS1 previously found to be significantly associated with hearing loss (n = 511), was marginally significant in an independent replication cohort (p = 0.06; n = 606)." (PMID 35322580, 2022). "Performing individual SNP association analysis on completely independent cohorts by excluding survivors in previous studies, the association between hearing loss and rs62283056 in WFS1 was borderline significant (p = 0.06)." (PMID 35322580, 2022). "Heterozygous mutations in WFS1 are also associated with a dominant form of hearing loss, known as low-frequency sensorineural hearing loss." (PMID 32938580, 2021). "Genetic variants in acylphosphatase 2 (ACYP2) and Wolframin ER transmembrane glycoprotein (WFS1) were identified as predictive markers for hearing loss." (PMID 30999660, 2019). "In the present study, WFS1 variants were screened in a large series of Japanese hearing loss (HL) patients to clarify the prevalence and clinical characteristics of DFNA6/14/38 and Wolfram-like syndrome." (PMID 29529044, 2018). "Loss of function mutation in the wfs1 gene encoding wolframin protein caused neurodegenerative disorders characterised by juvenile onset diabetes mellitus, optic atrophy, and hearing impairment." (PMID 24812634, 2014). "This study describes the phenotype of a family with autosomal dominant optic neuropathy and hearing impairment associated with a novel missense mutation in WFS1." (PMID 20069065, 2010). "Twenty-six other heterozygous WFS1 mutations linked to dominant low frequency sensorineural hearing loss have been described previously." (PMID 18518985, 2008). "Interestingly, the average audiogram of these cases showed mild-to-moderate low-frequency hearing loss, which is a well-known clinical characteristic of autosomal dominant WFS1 gene-associated hearing loss (DFNA6/14/38)." (PMID 39858604, 2025). "Variants of the WFS1 gene are known to cause low-frequency sensorineural hearing loss." (PMID 39200993, 2024). "WFS1 is also related to type 1 diabetes, hearing loss, blindness, and different eye problems." (PMID 37759745, 2023).
hearing loss (continued). "Potential causative variants were identified in genes associated with nonsyndromic hearing loss (CIB2, COL11A1, ILDR1, MYO15A, TMPRSS3, and WFS1), nonsyndromic hearing loss or Usher syndrome (CDH23, MYO7A, PCDH15, and USH2A), and other syndromic forms of hearing loss (CHD7, OPA1, and SPTLC1)." (PMID 34837038, 2022). "However, allele 6 (234 bp product) for marker D4S432 near the DFNA4/16/38 locus did cosegregate with hearing loss in the family, leading us to consider further the candidacy of the WFS1 gene by direct sequence analysis." (PMID 18518985, 2008). "With the exception of the p.R653C mutation in WFS1 and the p.D572N mutation in TMC1, the other five variants have not been previously reported to be associated with hereditary hearing loss." (PMID 25388789, 2014). "This type of hearing loss is uncommon and has been associated with only the DIAPH1, MYO7A and WFS1 genes." (PMID 22938506, 2012). "Despite the emergence of multiple animal models, none of them present with an early onset hearing loss, hampering the understanding of WFS1 role in the auditory pathway." (PMID 37386014, 2023). "We selected for further study the patients to which the GJB2 mutations did not explain their hearing impairment and the patients with variants in WFS1 gene." (PMID 33333757, 2020). "One patient clinically suspected of WS, presenting polydipsia, polyuria, and hearing impairment, was excluded because of lack of co-occurrences of DM and OA as well as WFS1 mutation." (PMID 29483894, 2018). "We performed a genetic screening of GJB2 gene (responsible for the major etiologies of hereditary hearing impairment among Romanians), GJB3, GJB6, POU3F4 and WFS1 genes." (PMID 33333757, 2020). "Thus, in order to link with certainty the Y669H mutation in WFS1 with symptoms of LFSNHL, future research will involve the construction of a transgenic mouse model carrying this mutation and the analysis of its phenotypic behavior, particularly in respect to symptoms of hearing impairment." (PMID 17517145, 2007). "Novel mutations were identified in multiple other genes - CDH23, MYO15A, WFS1, and TECTA - that are known to be responsible for hearing loss but are not routinely evaluated, largely because of their size." (PMID 21917145, 2011).
type 2 diabetes (42 papers, 2008 to 2026). "One of the recently published large studies that confirmed the association between WFS1 and type 2 diabetes included 81,412 type 2 diabetes patients and 370,832 healthy individuals of diverse ancestries." (PMID 37859980, 2023). "Global genome-wide association studies have listed at least 19 WFS1 variants that are associated with type 2 diabetes (T2D) and metabolic traits." (PMID 37859980, 2023). "WFS1 syndrome and its impact on type 2 diabetes research is well established, and many GWAS studies have shown the impact of WFS1 variations in the human population in the polygenic risk of type 2 diabetes." (PMID 37759745, 2023). "In recent years, some studies have also shown that WFS1 is linked to type 2 diabetes, autosomal dominant optic atrophy (ADOA), and psychiatric problems." (PMID 36564540, 2022). "Heterozygous mutations in WFS1 have been reported to be involved in less severe phenotypes including isolated adult-onset diabetes (OMIM #614296)." (PMID 35227307, 2022). "WFS1 gene is considered as genetic factor causing a predisposition to type 1 and type 2 diabetes in different populations." (PMID 35207731, 2022). "Common sequence variants in the WFS1 region were implicated in type 2 diabetes risk from genome‐wide association studies." (PMID 36208030, 2022). "Progressive decline in beta-cell function in Wfs1 KO animals eventually led to insulin deficiency and hyperglycemia at the age of 11.5 months: a key feature of type 2 diabetes." (PMID 34831417, 2021). "Among identified WFS1 SNPs, rs734312 (H611R) was shown to be associated with type 2 diabetes, with the minor allele conveying protective effects." (PMID 25211237, 2014). "Recently, single nucleotide polymorphisms (SNPs) of the WFS1 gene have also been implicated in the pathogenesis of type 2 diabetes." (PMID 23703906, 2013). "ATF6 is also the binding target of WFS1, a known type 2 diabetes susceptible gene, and mediates its effect on endoplasmic reticulum stress." (PMID 21211013, 2011). "WS1 is usually inherited in an autosomal recessive pattern, while dominant WFS1 variants were observed to associate with mild manifestations that appeared in an isolated manner, such as adult-onset diabetes, optic atrophy, congenital cataracts, and hearing impairment." (PMID 37277527, 2023). "The variant p.Trp314Arg of WFS1 was found in patients with type 2 diabetes." (PMID 36967753, 2023). "Furthermore, the DESIR (Data from Epidemiological Study on the Insulin Resistance Syndrome) prospective study demonstrated in French cohorts that allelic variations at three SNPs in the WFS1 gene were associated with incident type 2 diabetes." (PMID 37859980, 2023). "In addition, several rare sequence variants in WFS1 were also associated with type 2 diabetes risk in large exome sequencing studies." (PMID 36208030, 2022). "WFS1 was included as a candidate gene evaluated for association with type 2 diabetes." (PMID 35207731, 2022). "Since common variants of WFS1 correlate with type 2 diabetes (T2DM) risk, studying this rare disease may also have relevance to the pathogenesis of T2DM." (PMID 31937257, 2020). "In addition with two well replicated candidate genes TCF2 and WFS1, eighteen susceptible loci of type 2 diabetes were well recognized to date." (PMID 19862325, 2009). "Moreover, an association between WFS1 single nucleotide polymorphisms and an increased risk of type 2 diabetes has been identified in European populations." (PMID 18660851, 2008). "Furthermore, WFS1 is one of the genes reproducibly shown to be associated with Type 2 diabetes." (PMID 25211237, 2014). "The variant identified in ITA42 individuals causes a complete loss of the WFS1 protein due to an early stop signal, which is associated with recessive WSD and type II diabetes mellitus with neurodegeneration." (PMID 39000354, 2024). "WFS1-DM is usually mistakenly diagnosed as type 2 diabetes, and genetic testing is helpful for individualized treatment." (PMID 37277527, 2023).